TRIM28 (tripartite motif containing 28)
Diseases named in the same sentence as TRIM28 in open-access papers (continued):
Sharing a sentence is not in itself a finding about the gene and the disease.
tumor (continued). "The TCGA tumor types with high average mRNA-SI scores were expressing significantly higher levels of TRIM28 (r = 0.6523, p-value = 0.0002)." (PMID 33810347, 2021). "When we looked at the expression of TIF1 family members, only the level of TRIM28 was upregulated in all-score stemnessHIGH cohorts in most tumor types (except for three tumor types—OV, LUSC, and UVM)." (PMID 33810347, 2021). "Our results reveal a new necroptosis-mediated transcription circuit that is modulated by RIPK3 activation-dependent de-repression of TRIM28, which provides a mechanism to promote robust anti-tumor immunity and contributes to tumor immunogenicity." (PMID 34419074, 2021). "We also found GSC stemness-related genes, SOX2 and ID1, and MES subtype-related genes, THBS1 and CD44, enriched in the core of the tumours, together with higher TRIM28 expression." (PMID 34500575, 2021). "Our study also demonstrated that TRIM28 mRNA levels were significantly greater in most tumor tissues than in adjacent healthy tissues, especially in the case of LUAD." (PMID 33091876, 2020). "We also examined TRIM28 RNA levels in various tumor tissues and adjacent healthy tissues using the RNA sequencing data in TCGA." (PMID 33091876, 2020). "We then analyzed the relationship between TRIM28 expression and immune infiltration in 39 tumor types in the TIMER database." (PMID 33091876, 2020). "Most of the published data suggest that TRIM28 exerts oncogenic effects, and microarray analyses in a wide variety of tumors have revealed that TRIM28 mRNA levels are significantly greater in tumor tissues than in normal tissues." (PMID 33091876, 2020). "TRIM28 levels correlated negatively with the levels of 28 types of tumor-infiltrating lymphocytes across human tumors in the TISIDB database." (PMID 33091876, 2020). "Gene and protein levels of TRIM28 were higher in HCC tumours than their healthy counterparts, with high expression associated with a worse outcome for patients." (PMID 32731534, 2020). "The expression of TRIM28 was also detected by Western blot between a total of 20 matched human ESCC tumor tissues and adjacent NEE tissues." (PMID 30484263, 2019). "Tumor tissue also expressed high levels of the histone deacetylase HDAC5 and the SUMO/ubiquitin E3 ligase TRIM28, which is linked to STAT3 signaling, as well as low expression of the tumor suppressor PTGIS." (PMID 30645971, 2019). "Our approach offers insights into the tumor suppressive and tumor promoting effects of the highly pleiotropic protein TRIM28, thereby reinforcing its value as a prognostic biomarker and a potential therapeutic target." (PMID 29631612, 2018). "MAGEC2 was detectable in 26/53 (42.4%) cases, while TRIM28 was observed in almost all tumor samples." (PMID 30309319, 2018). "Expression status of TRIM28 in tumor epithelium and stromal fibroblasts was assessed using IHC in formalin fixed tissue and the epithelium to stroma protein expression ratio method." (PMID 29631612, 2018). "Co-immunoprecipitation assay was applied for detecting the endogenous interaction of MAGEC2 and TRIM28 in tumor cells." (PMID 30309319, 2018). "The gene expression pattern is remarkably similar, suggesting that TRIM28-mutant tumours 37T and W117 have the gene expression characteristics of the S1 subgroup." (PMID 29912901, 2018). "Low levels of TRIM28 in tumor stroma (high epithelium: stroma ratio) were found in 10 out of 19 cases." (PMID 29631612, 2018). "The proteomic network analysis of tumor epithelium in the TRIM28 low ratio group revealed statistically significant protein pair correlations in 69 signaling endpoints (ρ ≥ 0.75, p ≤ 0.01)." (PMID 29631612, 2018). "Remarkably, all four familial and one sporadic TRIM28-inactivated tumours had monomorphic epithelial morphology." (PMID 29912901, 2018).
tumor (continued). "Depletion of TRIM28 expression in tumor cells not only reduced the endogenous expression level of MAGEC2 protein, but also decreased the exogenous expression of MAGEC2 protein." (PMID 30309319, 2018). "We next compared expression levels of 30 signaling proteins between tumor epithelial and stromal compartments in either TRIM28 high or low ratio cases." (PMID 29631612, 2018). "We further detect the effects of knockdown or overexpression of TRIM28 on the levels of exogenous expression of MAGEC2 protein in tumor cells." (PMID 30309319, 2018). "Mechanistic studies indicate that the regulatory role of TRIM28 on MAGEC2 protein expression in tumor cells depends on proteasome-mediated pathway." (PMID 30309319, 2018). "Knockdown of FBP1 resulted in an increase in Ki-67 staining compared with the control group, but knockdown of TRIM28 decreased Ki-67 staining in tumor tissues compared with control tumors." (PMID 28394358, 2017). "Our results demonstrate that TRIM28 knockdown led to the downregulation of pluripotency markers, suggesting that tumor growth inhibition is due to reduction in the CSC pluripotency." (PMID 27845900, 2017). "Differential expression analysis of different tumor types from the Oncomine database suggested that TRIM28 is differentially expressed in 14 tumor types, including solid and hematopoietic tumors." (PMID 27845900, 2017). "As expected, TRIM28 depletion reduced the capacity of MDA-MB-231 cells to induce tumor growth, which implies that TRIM28 protein plays a role in the regulation of the CSC population." (PMID 27845900, 2017). "Our data demonstrate that the downregulation of TRIM28 gene expression reduced the ability of CSCs to self-renew that resulted in significant reduction of tumor growth." (PMID 27845900, 2017). "Compared with TRIM28WT cells, the ability of TRIM28-depleted cells to induce tumor growth was highly reduced." (PMID 27845900, 2017). "To date, many results have indicated that TRIM28 plays a critical role in the proliferation and differentiation of both normal and tumor cells." (PMID 27845900, 2017). "A total of 42% (47/111) of the patients for whom paired gene expression profiles of tumor and matched normal tissues are available showed more than 1.5-fold TRIM28 overexpression in their tumor tissues." (PMID 27845900, 2017). "The expression of Tripartite motif-containing protein 28 (TRIM28)/Krüppel-associated box (KRAB)-associated protein 1 (KAP1), is elevated in at least 14 tumor types, including solid and hematopoietic tumors." (PMID 27845900, 2017). "To assess whether Trim28 deletion and subsequent expression of ERVs or misregulated protein-coding genes could recruit immune cells to the tumor, we conducted immunostaining analysis for CD3 + T cells." (PMID 41508128, 2026). "However, long-term Trim28 deletion unexpectedly alters the tumor microenvironment and promotes tumor progression." (PMID 41508128, 2026). "The dsRNA staining intensity was high (> 50% of epithelial cells) in all Trim28-deleted NPp53T tumors, which contained foci with high signal intensity at 1 month after tumor induction, whereas the intensity was high or intermediate (1–50% of epithelial cells) in NPp53 tumors (arrows)." (PMID 41508128, 2026). "Interestingly, our findings showing increased resistance of TRIM28-KO clones to several chemotherapeutic agents appear to contradict the majority of studies reporting that TRIM28 suppression sensitizes tumor cells to treatment." (PMID 41303350, 2025). "The same pattern, albeit derived from a small number of cases, was seen in TRIM28 driven tumours." (PMID 39665570, 2025). "Notably, previous reports have demonstrated that TRIM28 supports both stemness and proliferation in such contexts, further supporting its role in coordinating immune escape and tumor progression." (PMID 41303350, 2025).
tumor (continued). "By contrast, in two non-predisposed children with biallelic TRIM28 driven tumours, a plethora of driver events emerged somatically, including high risk disease mutations." (PMID 39665570, 2025). "Therefore, our study adds XAF1 to TRIM28’s targets of tumor suppression function and identifies a novel mechanism for TRIM28-driven tumor progression." (PMID 39532800, 2024). "Conversely, TRIM28 can also exhibit tumor‐suppressive properties under certain conditions." (PMID 39534556, 2024). "TRIM28 plays a dual role in HCC, being associated with distant metastasis in HCC patients and is closely related to poor prognosis in HCC patients, while in a mouse HCC model, it acts as a tumor suppressor to prevent tumorigenic transformation." (PMID 39100077, 2024). "Utilizing combination chemotherapy involving etoposide along with a suitable TRIM28 S473p‐blocking peptide might aid in inducing tumor cell death." (PMID 39534556, 2024). "Notably, TRIM28 knockdown has been associated with increased responsiveness to anti‐PD‐1 therapy in immunocompetent mice, evidenced by higher levels of CD8+ T tumor‐infiltrating lymphocytes and decreased numbers of myeloid‐derived suppressor cells." (PMID 39534556, 2024). "Interestingly, in normal cells, SMURF2 has a negative impact on TRIM28 expression, whereas SMURF2 stabilizes TRIM28 in tumor cells." (PMID 39100077, 2024). "In vivo, knockdown of TRIM28 significantly inhibited the tumor growth and overexpression of IDO1 and SRF both could reverse proliferation inhibited by TRIM28 knockdown." (PMID 38947391, 2024). "Given that XAF1 is a stress-inducible growth inhibitor, it is likely that stress-induced high XAF1 could activate its tumor suppression signaling through TRIM28 destruction more efficiently in TRIM28-high versus TRIM28-low tumors." (PMID 39532800, 2024). "Advancing tumor treatment goals may involve the development of drugs or small molecules specifically targeting TRIM28." (PMID 39534556, 2024). "TRIM28 protein modulates the tumor growth of the CSC population." (PMID 39534556, 2024). "TRIM28 also promotes chemokine-driven myeloid-derived suppressor cell recruitment in the tumor microenvironment by interacting with RIPK1 (receptor interacting serine/threonine kinase 1) and facilitating its K63-linked polyubiquitination, thereby activating the NF-κB signaling pathway." (PMID 39160596, 2024). "There is an urgent need for the development of small molecule inhibitors targeting TRIM28, which could potentially serve as adjuncts to tumor therapy." (PMID 39534556, 2024). "XAF1 effect on TRIM28 level was also observed in various types of tumor cell lines." (PMID 39532800, 2024). "In addition, the expression level of TRIM28 affects the drug resistance of tumor cells, which seriously affects the anticancer effects of treatments, such as chemotherapy, targeted therapy, and immunotherapy." (PMID 39100077, 2024). "Also, we found that TRIM28 protein expression level was less in adjacent normal tissues than in tumor tissues of OV, PAAD, and SKCM." (PMID 37781084, 2023). "More and more studies have shown that TRIM28 plays a vital role in tumor genesis and progression." (PMID 36756159, 2023). "In addition to regulating tumor biology, TRIM28 was also found to have important implications for immunotherapy." (PMID 37781084, 2023). "The reason why TRIM28 has dual effects on tumor proliferation needs to be further explored." (PMID 36756159, 2023). "Moreover, we conducted the western blotting using paraffin-embedded tumor tissues and verified the higher expression of TRIM28 in tumor tissues than that in normal tissues in BLCA, BRCA, COAD, LUAD, PRAD, and UCEC." (PMID 37781084, 2023).
tumor (continued). "Recently, using the transcriptomic data from distinct types of solid tumors, we have reported that TRIM28 overexpression is significantly associated with an enriched stem cell-like phenotype regardless of the tumor type." (PMID 36674511, 2023). "We found that TRIM28 expression was higher in various tumor tissues than in normal tissues." (PMID 37781084, 2023). "In addition, rapamycin treatment markedly reduced the tumor burden in immuno-proficient mice bearing TRIM28-expressing tumors." (PMID 37357254, 2023). "Our results suggest that tumor-expressed TRIM28 spatially separated from MDSC." (PMID 37865804, 2023). "In recent years, studies have found that TRIM28 could regulate tumor progression and promote tumor growth by enhancing TRIM24 stability." (PMID 36690975, 2023). "While most reports showed TRIM28 promotes tumor progression, some reported otherwise." (PMID 36935008, 2023). "Moreover, silencing TRIM28 enhanced the efficacy of anti-PD-1 immunotherapy by reshaping the inflamed tumor microenvironment." (PMID 37865804, 2023). "Moreover, we also summarized the important role of TRIM28 in tumor stemness sustainability and immune regulation." (PMID 36756159, 2023). "TRIM28 can also play a role in tumor cell proliferation as a direct target of microRNAs." (PMID 36756159, 2023). "As expected, the knockdown of TRIM28 alone decreased tumor growth." (PMID 37865804, 2023). "Importantly, the combination of TRIM28 knockdown and anti-PD-1 significantly reduced tumor volume and weight, leading to a sustained reduction in tumor size throughout the treatment." (PMID 37865804, 2023). "Moreover, in a univariate Cox hazards analysis, tumor size, differentiation, depth of invasion and expression of lnc-TRIM28-14 were related to prognosis of the patients." (PMID 36690975, 2023). "Moreover, results from the in vivo tumor models and human G.C. further validated that TRIM28 mediates the immune response by upregulating PD-L1 expression." (PMID 37357254, 2023). "In addition, significant differences were also found among the TRIM28 levels and tumor staging groups (P = 0.000186) according to the GEPIA2 datasets." (PMID 37870748, 2023). "These values are calculated using all tumor-specific L1 inserts, which include those that may have happened before the increase in the TRIM28 expression occurred in any given tumor." (PMID 37070200, 2023). "The result showed TRIM28 overexpression reduced tumor growth." (PMID 36935008, 2023). "Additionally, TRIM28 expression was positively related to tumor purity and the presence of CD8+ T cells, CD4+ T cells, macrophages, neutrophils, and dendritic cells in GBM and LIHC (all p values < 0.001)." (PMID 37781084, 2023). "It is undeniable that TRIM28 may have an important effect on tumor migration and invasion by regulating EMT." (PMID 36756159, 2023). "However, in in vivo experiments, a lower TRIM28 level was shown to be related to weaker self-renewal and tumor formation properties." (PMID 37492743, 2023). "Here, we reviewed the role of TRIM28 in tumor proliferation, migration, invasion and cell death." (PMID 36756159, 2023). "To determine whether TRIM28-mediated increased of PD-L1 expression contributes to the immune evasion of the tumor cells, we blocked PD-L1 expression." (PMID 37357254, 2023). "TRIM28 alteration exhibited co-occurrence instead of mutual exclusivity with a large number of immune checkpoint components and tumor-infiltrating immune cells, especially B cells, were found to serve roles in patients with HCC with different TRIM28 expression levels." (PMID 37870748, 2023). "Furthermore, ectopic expression of TRIM28 led decreased infiltration of CD8+ tumor-infiltrating lymphocytes." (PMID 37357254, 2023). "Activated RIPK3 could phosphorylate TRIM28 and increase the production of immunostimulatory cytokine in the tumor microenvironment, then emerge strong cytotoxic anti-tumor immunity." (PMID 36611858, 2022).
tumor (continued). "TRIM28 expression levels correlated with the tumor grade and presented a marker for poor prognosis." (PMID 36139694, 2022). "In summary, these results showed TRIM28 was a positive predictive tumor marker for LIHC patients." (PMID 36238495, 2022). "To validate TRIM28's prognostic influence in LIHC, we analyzed the TCGA datasets to determine how TRIM28 expression differed between normal and tumor tissue and discovered that the level of TRIM28 was increased in all LIHC tissues compared to normal liver tissue." (PMID 36238495, 2022). "For instance, RIPK3 activation-triggered de-inhibition of tripartite motif protein 28 (TRIM28) in tumor cells results in increased immunostimulatory cytokine production within the tumor microenvironment and thus contributes to robust cytotoxic antitumor immunity." (PMID 35662734, 2022). "We analysed whether the TRIM28 mRNA expression levels at the rim and in the core of the tumour tissues differ in 3 GB samples (GB1, GB2, GB3)." (PMID 34500575, 2021). "In general, our results reveal the mechanism of telomere heterochromatin maintenance and its effect on ALT, and TRIM28 may serve as a target for the treatment of ALT tumor cells." (PMID 34330324, 2021). "Consequently, TRIM28 knockdown decreased colony formation of AR-dependent PC cells and diminished xenograft tumor development." (PMID 34208621, 2021). "Moreover, we compared the average mRNA-SI value with the mean expression of TIF1 family members across TCGA tumor types and observed a significant positive correlation only for TRIM28." (PMID 33810347, 2021). "Furthermore, TRIM28, a transcriptional corepressor, reportedly promotes tumor proliferation and metastasis." (PMID 33221751, 2020). "Interestingly, the high aggressiveness of CRC tumors with high TRIM28 expression levels is probably mediated by TRIM28 dependent induction of tumor promoting signaling pathways in the tumor stroma and pro-survival pathways in tumor epithelial cells." (PMID 33066016, 2020). "Their results also showed that the TRIM28-overexpressing tumors grew at a much higher rate, as determined by size and weight, than the control tumors, whereas the tumors formed by TRIM28-silenced cells were smaller and had lower tumor weights than those formed from shRNA-vector control cells." (PMID 30484263, 2019). "TRIM28 promotes PCa cell proliferation in vitro and xenograft tumor growth in vivo." (PMID 30479348, 2018). "The combination of frameshift mutations and loss of heterozygosity or promoter methylation of the non-variant allele indicates complete loss of TRIM28 function in the tumours, that was confirmed by immunohistochemistry." (PMID 29912901, 2018). "Here we report a mean of four (range 0–12) high quality somatic variants per tumour, but unusually the two TRIM28-mutant tumours analysed by exome sequencing revealed no additional mutations." (PMID 29912901, 2018). "Here, we found that expression of MAGEC2 protein in tumor cells requires the existence of TRIM28." (PMID 30309319, 2018). "We found modulation of several signaling pathways associated with TRIM28, which may be attributed to the pleiotropic properties of TRIM28 through its translational suppression of the family of KRAB domain transcription factors in tumor stromal compartments." (PMID 29631612, 2018). "More recently, tumor promoting effects of TRIM28 were observed in glioma and breast cancer." (PMID 29631612, 2018). "Future studies could lead to identification and reassurance of families that carry TRIM28 mutations, and to the use of reduced intensity of treatment for children who develop TRIM28-null tumours." (PMID 29912901, 2018). "By comparison, the 16 sequenced tumours without TRIM28 variants had a mean and median of 4 (range, 0–12) detected somatic variants." (PMID 29912901, 2018).